RS1 (retinoschisin 1)
Description:
Binds negatively charged membrane lipids, such as phosphatidylserine and phosphoinositides (By similarity). May play a role in cell-cell adhesion processes in the retina, via homomeric interaction between octamers present on the surface of two neighboring cells. Required for normal structure and function of the retina.
Synonyms: XLRS1; RS
Tractability: Antibody: UniProt places it where antibodies can reach, with high confidence; UniProt predicts a signal peptide or a membrane-spanning region; its Gene Ontology location is reachable by antibodies, with medium confidence.
Gene: Protein-coding gene on chromosome X (18,639,688 to 18,672,108, reverse strand). Ensembl gene ENSG00000102104.
Subcellular location: Secreted; Cell membrane
Gene Ontology:
Molecular function: phospholipid binding; phosphatidylserine binding; phosphatidylinositol-3,4-bisphosphate binding; protein-containing complex binding
Biological process: protein homooligomerization; visual perception; cell adhesion; eye development; retina layer formation
Cellular component: external side of plasma membrane; extracellular region; neuron to neuron synapse; photoreceptor inner segment; plasma membrane; cell surface
Gene-disease validity (ClinGen):
ClinGen rates the evidence that RS1 causes each of these diseases.
X-linked retinoschisis (X-linked): Definitive. A genetic ocular disease that is characterized by reduced visual acuity in males due to juvenile macular degeneration.
Homologues: Orthologues: chimpanzee RS1 (100% identical), macaque RS1 (100% identical), rat Rs1 (96% identical), mouse Rs1 (96% identical), dog RS1 (96% identical), pig RS1 (96% identical), rabbit RS1 (96% identical), guinea pig RS1 (95% identical), tropical clawed frog rs1 (71% identical). Paralogues in human: DCBLD1 (30% identical).
Diseases named in the same sentence as RS1 in open-access papers:
RS1 is named in the same sentence as 41 diseases in open-access papers, as found by Europe PMC text mining. Sharing a sentence is not in itself a finding about the gene and the disease. The quoted sentences say what the papers report.
X-linked retinoschisis (47 papers, 2006 to 2025). "X-linked retinoschisis (XLRS) is a vitreoretinal dystrophy caused by RS1 gene mutations which disrupt retinoschisin-1 (RS1) function." (PMID 39473494, 2024). "Other diagnoses detected among Africans include albinism (GPR143 and TYR genes), Senior–Loken Syndrome (NPHP4 gene), and X-linked retinoschisis (RS1 gene)." (PMID 36836473, 2023). "X-linked retinoschisis is caused by pathogenic variants in the RS1 gene (OMIM #300839, consisting of six exons) that encodes for retinoschisin, a cell surface protein found in photoreceptors as well as bipolar cells." (PMID 37298674, 2023). "X-linked juvenile retinoschisis (XLJR) is an inherited bilateral vitreoretinal degeneration caused by mutations in the RS1 gene, which encodes the retinoschisin protein." (PMID 37189561, 2023). "Pathologic mutations in RS1 cause X-linked juvenile retinoschisis (XLRS), a hereditary retinal dystrophy in young males." (PMID 35876901, 2022). "X-linked retinoschisis (XLRS) is an early onset macular dystrophy associated with abnormal or deficient retinoschisin protein (RS1), which is mainly secreted by photoreceptors and is involved in retinal intercellular adhesion and matrix architecture." (PMID 36477475, 2022). "These six SP variants were in the CRB1 (early-onset retinal dystrophy), NDP (familial exudative vitreoretinopathy) (FEVR), FZD4 (FEVR), EYS (retinitis pigmentosa), and RS1 (X-linked juvenile retinoschisis) genes." (PMID 36362148, 2022). "For example, solid lipid nanoparticles carrying the human RS1 gene have been shown to mediate structural improvement in the mouse Rs1h knockout model of X-linked juvenile retinoschisis." (PMID 33815052, 2021). "Other studies highlighted the role of the Na/K-ATPase in photoreceptor function and survival, as the mutations in the retinoschisin (RS1) gene cause X-linked juvenile retinoschisis, a hereditary retinal dystrophy." (PMID 30696106, 2019). "X-linked retinoschisis (XLRS) is a retinal degenerative disorder caused by mutations in RS1 gene leading to splitting of retinal layers (schisis) which impairs visual signal processing." (PMID 29851975, 2018). "In some cases, only a single gene is related to the condition, such as the RS1 gene in X-linked retinoschisis; as such, direct Sanger Sequencing may be the first choice." (PMID 37298674, 2023). "Loss of retinoschisin (RS1) function underlies X-linked retinoschisis (XLRS) pathology." (PMID 36227606, 2022). "Mutations in RS1 lead to juvenile retinoschisis, a form of early-onset macular degeneration." (PMID 35358180, 2022). "Mutations in RS1, the gene encoding retinoschisin, cause X-linked retinoschisis (XLRS), a retinal disease characterized by the splitting of retinal layers and loss of visual acuity." (PMID 40558505, 2025). "An illustration of this phenomenon is X-linked retinoschisis (XLRS), a disorder precipitated by loss-of-function mutations in the RS1 gene located on the X chromosome." (PMID 39451224, 2024). "X-linked retinoschisis (XLRS), due to mutations in the RS1 gene, is a common genetically determined form of macular degeneration." (PMID 37069516, 2023). "X-linked retinoschisis (XLRS) is a monogenic inherited retinal disease (IRD) caused by mutations in the RS1 gene and has a prevalence of 1/5,000 to 1/20,000 in males." (PMID 38351967, 2023). "We generated a Long Evans transgenic rat with targeted deletion of the whole Rs1 exon-1 and evaluated the pathological retinal phenotype of this Rs1-/Y rat model of X-linked retinoschisis (XLRS)." (PMID 36360232, 2022). "X-linked retinoschisis (XLRS) is a retinal disorder caused by mutations in RS1 gene (encoding retinoschisin) leading to splitting of retinal layers which impairs visual signal processing." (PMID 34039417, 2021). "X-linked juvenile retinoschisis (XLRS) is a macular degenerative disease that occurs exclusively in males and is associated with mutations in the RS1 gene." (PMID 37176614, 2023).
X-linked retinoschisis (continued). "X-linked juvenile retinoschisis (XLRS), a degenerative retinopathy, is linked to mutations in the RS1 (Retinoschisin 1) gene." (PMID 34638582, 2021). "X-linked retinoschisis (XLRS) is the most prevalent juvenile vitreoretinal degeneration in males and is caused by mutations in an extracellular adhesion protein, retinoschisin (RS1), normally expressed in the retina by photoreceptors and bipolar, amacrine, and ganglion cells." (PMID 31739639, 2019). "Individuals with X-linked retinoschisis (XLRS), an early onset macular degeneration associated with mutations in RS1, show similar features including the splitting of the retinal layers most pronounced in the macula, a reduction in the ERG b-wave amplitude, and significant loss in central vision." (PMID 26812435, 2016). "X-linked retinoschisis (XLRS) is an X-linked recessive vitreoretinal dystrophy characterized by macular schisis, caused by mutations in the RS1 gene, which is responsible for encoding retinoschisin, a protein essential for retinal cell adhesion and structural integrity." (PMID 41440982, 2025). "designed supramolecular nanoparticle (SMNP) vectors for codelivery of CRISPR/Cas9 and RS1 gene, presenting a potential non-viral therapeutic solution for X-linked juvenile retinoschisis (XLRS)." (PMID 38983081, 2023). "Regarding macular dystrophy X-linked retinoschisis (XLRS), the loss of the extracellular matrix protein retinoschisis 1 (RS1) was compensated by AAV-based delivery of RS1 to the eye of RS1 knockout mice, which generated significant improvement in retinal structure and function." (PMID 36992407, 2023). "Sequencing of the RS1 gene revealed no pathogenic variants, effectively ruling out co-existing X-linked retinoschisis." (PMID 32787478, 2020). "This may be advantageous for retinas that are particularly at risk for retinal detachment, such as in X-linked retinoschisis (XLRS), which is caused by mutations in retinoschisin 1 (RS1)." (PMID 28134823, 2017). "X-linked retinoschisis (XL-RS) is an IRD caused by mutations in the retinoschisin 1 (RS1) gene, which encodes Retinoschisin-1, a protein essential for the retinal structure and cell adhesion." (PMID 39598155, 2024). "X-linked retinoschisis (XLRS, OMIM 312,700) is a monogenetic hereditary retinal dystrophy with an estimated prevalence between 1 in 15,000 and 1 in 30,000 caused by mutations of the retinoschisis-1 gene (RS1)." (PMID 37294434, 2023).
retinoschisis (21 papers, 2006 to 2025). An inherited or acquired disorder characterized by splitting of the retina into two layers. "Mutations in the X-linked gene, RS1, are the most common cause of retinoschisis, usually in male patients." (PMID 38790275, 2024). "Dysfunction of RS1 (retinoschisin 1) causes a structurally vulnerable retina and results in congenital retinoschisis." (PMID 38034549, 2023). "In summary, our studies demonstrated that a novel nonsense mutation in RS1 gene (c.195T >G) would lead to human retinoschisis." (PMID 29379415, 2017). "RS1 (Retinoschisin1) is the gene implicated in XLRS and mutations in this gene have accounted for retinoschisis in most cases." (PMID 28450823, 2017). "Retinoschisis, which affects retinal architecture, is another disease nearing clinical application, following successful gene therapy in the Rs1-KO mouse model." (PMID 25650393, 2015). "The mechanisms of the involvement of RS1 protein in congenital retinoschisis remain uncertain." (PMID 36212125, 2022). "All 10 probands with hemizygous RS1 mutations (the clinical data of 4 probands were not available) had clinical symptoms and signs of retinoschisis." (PMID 22245991, 2012). "Consequently, the main point in avoiding retinoschisis is the presence of the functional RS1 protein." (PMID 18728755, 2008). "Importantly, Rs1-KO mouse models have served to show the possibility of gene therapy via intravitreal delivery of viral vectors carrying the normal gene, in preparation for application of this treatment in patients with retinoschisis." (PMID 25650393, 2015). "However, in some patients, pRNFL thinning is diffuse and may be associated with specific RS1 pathogenic variants leading to optic atrophy independent of retinoschisis." (PMID 39209741, 2024). "The pathogenesis of retinoschisis in our KSS patient is unclear, but we can venture some hypotheses based on our current understanding of the RS1 protein’s function." (PMID 32787478, 2020). "Similar results were reported after the NEI sponsored X-linked retinoschisis trial in which ocular inflammation was reported as the main adverse event following treatment, and the patients’ sera tested positive for neutralizing antibodies against the AAV8 capsid but not the RS1 protein." (PMID 34768969, 2021).
cyst (4 papers, 2022 to 2024). A sac-like closed membranous structure that may be empty or contain fluid or amorphous material. "By 1 MPI, a critical time point in cyst development as evidenced by natural history data, eyes across all experimental groups—hypertonic buffer, isotonic buffer, and sham puncture, —had a reduction in cyst severity compared to untreated Rs1-KO eyes." (PMID 39473494, 2024). "It is worth noting that our group has previously reported the beneficial effects of injecting buffer diluent alone on cyst severity in Rs1-KO mice." (PMID 38414621, 2024). "Initially, a subretinal injection of a 2 × 109 vg/mL dose of AAV2/4-EF1α-RS1 in Rs1-KO mice did improve functional metrics such as cyst severity and cone electrical functioning, when compared to untreated Rs1-KO controls." (PMID 39473494, 2024). "However, only hypertonic buffer-injected eyes maintained a reduction in cyst severity over untreated Rs1-KO eyes to 2 MPI." (PMID 39473494, 2024). "This reduction in cyst burden was particularly noteworthy because it coincided with the critical cyst developmental period around 2-months of age, a time when peak cyst formation is typically observed in Rs1-KO mice." (PMID 39473494, 2024). "Most XLRS patients have schisis cavities as the predominant clinical finding, yet Rs1-KO mouse demonstrate decrease in cyst volume after four to six months of life with concomitant thinning of the retina and widespread loss of crisp retinal lamination regardless of treatment status." (PMID 36477475, 2022). "In a distinct study conducted by our research team, which investigated the buffer tonicity as a treatment to Rs1-KO mice, it was observed that mice treated with buffer (whether hypertonic or isotonic) displayed reduced cyst severity and improved cone ERG function in comparison to untreated eyes." (PMID 38414621, 2024). "In a recently reported AAV2-mediated RS1 gene augmentation trial, clinical response at 12 months was demonstrated only for two endpoints: static perimetry, with two responders of 25 participants, and reduction in cyst cavity volume on SD-OCT, with one responder of 23 participants." (PMID 37396901, 2023). "Interestingly, hypertonic buffer-injected eyes exhibited a reduced cyst burden at 3 WPI, compared to untreated Rs1-KO eyes." (PMID 39473494, 2024).
hereditary retinal dystrophy (4 papers, 2017 to 2026). "X‐linked juvenile retinoschisis (XLRS) is a hereditary retinal dystrophy in young males, caused by mutations in the RS1 gene." (PMID 27995734, 2017). "Integrated analysis of RNA-seq data from both Gm20541 and Msx2 mutant retinas indicated that ZNF124 is essential for maintaining normal retinal function by regulating Msx2 transcription, which in turn controls the expression of murine homologues of retinal dystrophy genes Rs1, Pde6g, and Pdc." (PMID 41708596, 2026).
retinal detachment (4 papers, 2017 to 2023). An eye emergency condition which may lead to blindness if left untreated. "In the candidate gene approach, COL9A2, COL9A3, NHEJ1, RS1 and NDP genes were investigated based on their known associations with RD and retinal detachment in dogs and humans." (PMID 33945575, 2021).
retinal degeneration (3 papers, 2022 to 2024). Degeneration of the retina. "The mechanism of RS1-associated retinal degeneration is not fully understood." (PMID 38816767, 2024). "The gene heatmap depicting the proteins involved in key functions such as significant activation of retinal degeneration in the KO group was attributed to two up-regulated (retinoschisin (Rs1) and ubiquilin-1 (Ubqln1)) and two down-regulated (Gucy2e and GNB1) proteins." (PMID 36359890, 2022).
retinal diseases (3 papers, 2017 to 2024). "X-linked juvenile retinoschisis (XLRS) is a retinal disease caused by mutations in the gene encoding retinoschisin (RS1), which leads to a significant proportion of visual impairment and blindness." (PMID 29379415, 2017). "In contrast, we have shown previously that Rs1-KO mice have worse functional vision than normal controls at 4–6 months of age in the dark condition, and that this swim assay is sensitive enough to detect differences in the rates of visual decline in other inherited retinal diseases." (PMID 38414621, 2024).
Familial exudative vitreoretinopathy (2 papers, 2020 to 2022). Familial exudative vitreoretinopathy (FEVR) is a rare hereditary vitreoretinal disorder characterized by abnormal or incomplete vascularization of the peripheral retina leading to variable clinical manifestations ranging from no effects to minor anomalies, or even retinal detachment with blindness. "The SP sequences of the CRB1 (early-onset retinal dystrophy), NDP (familial exudative vitreoretinopathy) (FEVR), FZD4 (FEVR), EYS (RP), and RS1 (XLRS) genes were affected." (PMID 36362148, 2022).
fibrous dysplasia (2 papers, 2010 to 2014). A genetic, non-inheritable disorder caused by osteoblastic differentiation defects that result in the replacement of bone marrow and trabecular bone by fibrous stroma and immature bone. "In this study, we investigated the cause of fibrous dysplasia-associated hearing loss using the ColI(2.3)+/Rs1+ mouse model that develops invasive FD-like lesions." (PMID 24788917, 2014). "These ColI(2.3)+/Rs1+ mice showed dramatic bone lesions that histologically and radiologically resembled fibrous dysplasia." (PMID 24788917, 2014). "Rs1 expression in osteoblasts induced a dramatic age-dependent increase in trabecular bone with features resembling fibrous dysplasia." (PMID 20200944, 2010).
Leber congenital amaurosis (2 papers, 2022 to 2025). Leber congenital amaurosis (LCA) is a retinal dystrophy defined by blindness and responses to electrophysiological stimulation (Ganzfeld electroretinogram (ERG)) below threshold, associated with severe visual impairment within the first year of life. "Vessel density was found to be highest in EFEMP1, BEST1, TIMP3, RS1, and PRPH2 (11.0%, 10.4%, 10.1%, 10.1%, 9.2%) and was lower in retinitis pigmentosa (RP) and Leber congenital amaurosis genes." (PMID 39896422, 2025).
McCune-Albright syndrome (2 papers, 2010 to 2011). McCune-Albright syndrome (MAS) is classically defined by the clinical triad of fibrous dysplasia of bone (FD), cafe-au-lait skin spots, and precocious puberty (PP). "The observed low levels of Rs1 expression in mouse tissues likely accounts for the absence of embryonic lethality and other pathology we would have expected if our model mimicked McCune-Albright syndrome." (PMID 21375737, 2011).
retinoblastoma (2 papers, 2024 to 2025). A malignant tumor that originates in the nuclear layer of the retina. "Interestingly, treatment of Y-79 cells, human retinoblastoma cells that endogenously express α3β2, with recombinant RS1 resulted in decreased expression of the pro-apoptotic BCL-2 associated X protein (BAX)." (PMID 40558505, 2025).
alexithymia (1 paper, 2026). An agnosia that is a deficiency in understanding, processing, or describing emotions. "Our study provides novel evidence on the neural dynamics underlying difficulties in emotion processing in ASD individuals, highlighting that differential intrinsic activations of the rS1 are causally involved in such difficulties, and suggests that they are mediated by alexithymia." (PMID 41684326, 2026).
brain ischemia (1 paper, 2020). Diminished or absent blood supply to the brain caused by obstruction (thrombosis or embolism) of an artery resulting in neurologic damage. "Changes in the proliferation of neural stem/progenitor cells during the first weeks following photothrombosis-induced brain ischemia and in vitro effects of spidroin rS1/9 in rat primary neuronal cultures were the subject of the study." (PMID 33015039, 2020). "We analyzed the amount of NCAM in the hippocampus and found its significant increase after brain ischemia, as well as after injection of rS1/9 hydrogel in the area of ischemic damage." (PMID 33015039, 2020). "We examined changes in the proliferation of neural stem/progenitor cells during the first weeks following photothrombosis-induced brain ischemia and also in vitro effects of spidroin rS1/9 in rat primary neuronal cultures." (PMID 33015039, 2020). "To determine alterations in the subtypes of cells in the hippocampus following brain ischemia and rS1/9 treatment, we analyzed the levels of a number of proteins that are markers of brain cells." (PMID 33015039, 2020).
chronic liver failure (1 paper, 2022). Liver failure that develops slowly and gradually for some time, possibly for years, often as the result of cirrhosis, or malnutrition. "The results of biochemical and histological studies in animals with chronic liver failure modeling reveal expressed functional activity of CECs containing the microgel based on RS rS1/9 and cellular material (allogeneic LC and MMSC BM in a ratio of 5:1)." (PMID 35956695, 2022).
diabetes (1 paper, 2022). "Notably, two differentially expressed proteins GUCY2F and RS1 were found in both MAM fractions from Type 2 diabetic mouse brain or Type 1 diabetic rat retina, suggesting that these proteins may play a role in the pathogenesis of diabetes-associated neurodegeneration." (PMID 36139394, 2022).